CD44 (CD44 molecule (IN blood group))
Diseases named in the same sentence as CD44 in open-access papers (continued):
Sharing a sentence is not in itself a finding about the gene and the disease.
knee osteoarthritis (1 paper, 2024). "Expression of CD44 in articular cartilage is associated with disease severity in knee osteoarthritis Expression of CD44 in articular cartilage is associated with disease severity in knee osteoarthritis Mod." (PMID 39281650, 2024).
Krabbe disease (1 paper, 2022). A lysosomal disorder that affects the white matter of the central and peripheral nervous systems. "iPSCs from three healthy controls and two donors with infantile onset Krabbe disease successfully differentiated into astrocytes that expressed appropriate lineage markers vimentin, S100β, CD44, and GLAST." (PMID 35921286, 2022).
lactic acidosis (1 paper, 2010). Metabolic acidosis characterized by the accumulation of lactate in the body.
leiomyoma (1 paper, 2022). A well-circumscribed benign smooth muscle neoplasm characterized by the presence of spindle cells with cigar-shaped nuclei, interlacing fascicles, and a whorled pattern. "We isolated leiomyoma stem cells by flow cytometry using DyeCycle Violet staining and Stro‐1/CD44 surface markers." (PMID 35118811, 2022). "In addition, specific cell surface markers such as Stro‐1 and CD44 have been used to identify myometrial and leiomyoma stem cells since cells displaying these markers possess stem or progenitor cell features." (PMID 35118811, 2022).
leiomyomatosis (1 paper, 2021). A condition characterized by the presence of numerous small benign smooth muscle neoplasms located throughout the body. "Further studies should examine the intravascular transferability of CD44-positive mesenchymal tumor cells isolated from tissues of intravenous leiomyomatosis (i.e., uterine mesenchymal tumor stem-like cells)." (PMID 34563053, 2021).
limb ischemia (1 paper, 2022). A ischemia that involves the limb. "In conclusion, HA facilitates angiogenesis of MSCs-ECFCs, and this positive effect be associated with activation of the CD44/miR-139-5p pathway, providing a promising strategy for improving severe limb ischemia." (PMID 35350177, 2022).
Lipedema (1 paper, 2023). Disorder of adipose tissue characterized by symmetric and bilateral enlargement of the lower extremities due to abnormal deposition of subcutaneous fat often in obese women. "However, it was shown that CD74, which builds a complex with CD44, fosters cell survival and inflammation, which may apply to adipose tissue in lipedema patients." (PMID 37887430, 2023).
Listeria infection (1 paper, 2018). "A CD44-negative tumor cell line, embryonic fibroblasts and bone marrow-derived macrophages from cd44-/- mice were reduced in their response to IFN-γ, to viral DNA fragments and to Listeria monocytogenes infection." (PMID 30540779, 2018). "Indeed, Listeria infection led to increased expression of both IFI16 and IFN-β in WT macrophages carrying CD44." (PMID 30540779, 2018).
macular oedema (1 paper, 2023). "Taken together, our results suggest that nAMD patients had significantly higher intraocular levels of VCAM-1, ICAM-1, CD44 and CD62L and that higher level of VCAM-1 is related to macular fibrosis and increased central retinal thickness (a sign of macular oedema)." (PMID 37985993, 2023).
malnutrition (1 paper, 2021). Inadequate nutrition resulting from poor diet, malabsorption, or abnormal nutrient distribution. "In thymus, malnutrition affects the four stages of maturation according to the differential expression of CD44 and CD25: CD44+CD25− (DN1), CD44+CD25+ (DN2), CD44−CD25+ (DN3) and CD44−CD25− (DN4)." (PMID 34458307, 2021).
meningoencephalitis (1 paper, 2018). Inflammation of the meninges and brain, generally secondary to an infectious cause. "Deletion of cd44 ameliorated meningoencephalitis induced by Cryptococcus neoformans." (PMID 30540779, 2018).
middle ear infection (1 paper, 2019). "Since mucosal hyperplasia and leukocyte infiltration of the middle ear cavity are major features of otitis media, we evaluated the role of CD44 in the pathophysiology and course of this disease in a mouse model of middle ear infection." (PMID 31226944, 2019).
mood disorder (1 paper, 2019). A cognitive disorder a disturbance in which the person's mood is hypothesized to be the main underlying feature. "Further work is encouraged to delineate the functional impact of excitatory amino acid transporter genetic variation on CD44 associated physiology and glutamatergic neurotransmission, specifically glutamate–glutamine cycling, and its contribution to subphenotypes of mood disorders." (PMID 31123248, 2019).
mucinous tumors (1 paper, 2021). "CD44 expression was cytoplasmic and membranous (5/22, 22.7%) or only membranous (9/22, 40.9%), with an intensity greatest in mucinous tumors (mean intensity score 2.5)." (PMID 34069167, 2021).
muscular dystrophy (1 paper, 2023). Muscular dystrophy (MD) refers to a group of more than 30 genetic diseases characterized by progressive weakness and degeneration of the skeletal muscles that control movement. "Collectively, these results suggest that the Spp1 pathway is a key regulator of gal-3+ macrophage and FAP interactions during muscular dystrophy and that Spp1 signals primarily through CD44 and a subset of integrin heterodimers to control FAP differentiation." (PMID 37418531, 2023).
Mycobacterium infection (1 paper, 2017). Infections with bacteria of the genus Mycobacterium. "A long-term immune response based on the presence of memory (CD44+ CD62LLow CD25−) CD4+ T and (CD44+ CD62LLow CD45R−) CD8+ Tcells is examined to determine protection from mycobacterium infection." (PMID 28224119, 2017).
myeloid sarcoma (1 paper, 2023). A tumor mass composed of myeloblasts or immature myeloid cells.
myxoid liposarcoma (1 paper, 2022). A liposarcoma characterized by the presence of round non-lipogenic primitive mesenchymal cells and small signet ring lipoblasts within a myxoid stoma with a branching vascular pattern. "We validated CD44 as a target gene of JAK1/2 inhibition and as a potential cancer stem cell marker in myxoid liposarcoma." (PMID 35186752, 2022).
nasopharyngitis (1 paper, 2015). An inflammatory process that affects the nasopharynx. "First, we immunohistochemically compared NPC sections with nasopharyngitis sections using an anti-CD44 antibody." (PMID 26202311, 2015). "In the NPC sections, we found groups of epithelial cancer cells that were CD44-positive, some of which co-expressed the stem cell biomarker OCT4; the two biomarkers were rarely expressed in nasopharyngitis sections." (PMID 26202311, 2015).
neck tumor (1 paper, 2018). "Selective expression of PD-L1 was observed on CD44+ head and neck tumor cells compared with CD44− tumor cells." (PMID 30283733, 2018).
Neisseria meningitidis infection (1 paper, 2025). "ICAM-1 and CD44 are massively recruited to bacterial adhesion sites during Neisseria meningitidis infection, together with the ERM proteins (ezrin), to regulate host inflammatory response by blocking the transendothelial migration of leukocytes." (PMID 41440381, 2025).
nodular melanomas (1 paper, 2008). "CD44 was significantly co-expressed with αv-integrin (p = 0.011) in nodular melanomas." (PMID 19061491, 2008).
odontogenic cyst (1 paper, 2023). A cyst in the jaw that arises from tissues of tooth development. "Calcifying odontogenic cysts were positive for CD44, but negative in all or most cases for OCT4 and SOX2, respectively." (PMID 37761874, 2023).
oncocytoma (1 paper, 2013). "CD44 is a hyaluronic acid receptor whose mRNA levels in tumors can distinguish between RCC subtypes and RCC subtypes from oncocytoma and predict RCC metastasis." (PMID 23442546, 2013).
parathyroid neoplasms (1 paper, 2022). "Only few scientific teams have studied CD44 expression in parathyroid tumours." (PMID 35805976, 2022).
pharyngeal squamous cell carcinoma (1 paper, 2018). A squamous cell carcinoma that arises from the pharynx. "This premise is carried further here to demonstrate that EMT and the stem cell marker CD44 are highly activated in the primary tumor of HPV-negative pharyngeal squamous cell carcinoma but are turned back in a metastasis." (PMID 29693014, 2018).
phospholipidosis (1 paper, 2020). "An increased accumulation of lipids and oxidized lipids in the cell are signs of a foamy macrophage and phospholipidosis, and this was further supported by the increased labeling of NBD-PE by CD44−/− AMs." (PMID 32082314, 2020).
pilomatricomas (1 paper, 2016). "At 4 weeks, back skin of Lgr5 KI/R26R-tdTomato/Ctnnb1lox(ex3)/+ mutant mice showed comprehensive dermal ECM remodeling and CD44 expression in the lower dermis surrounding the pilomatricomas, while the upper dermis contained only mature collagen." (PMID 26771241, 2016).
prediabetes (1 paper, 2019). "The expression of genes involved in human T-cell activation, including CD44 and CD69, as well as proinflammatory cytokines, was significantly higher in patients with prediabetes." (PMID 30867412, 2019).
proliferative vitreoretinopathy (1 paper, 2019). Vitreoretinal membrane shrinkage or contraction secondary to the proliferation of primarily retinal pigment epithelial cells and glial cells, particularly fibrous astrocytes, followed by membrane formation. "Since oxidative stress may induce wet and dry AMD, both, along with proliferative vitreoretinopathy, CD44 aptamer may be applicable as a carrier for targeted lysosomal delivery of therapeutic cargoes in ocular diseases showing oxidative stress in RPE cells." (PMID 31080896, 2019).
prostatic intraepithelial neoplasia (1 paper, 2020). "Immunohistochemical analysis of CD44v5 expression in radical prostatectomy specimens has revealed decreased CD44 scores during de-differentiation from low- to high-grade prostatic intraepithelial neoplasia." (PMID 33218199, 2020).
Q fever (1 paper, 2023). A bacterial infection caused by Coxiella burnetii. "For example, CD44–ezrin interactions are involved in the internalization process of Coxiella burnetii, the etiologic agent of Q fever, in non-phagocytic cells." (PMID 37894408, 2023).
relapsing (1 paper, 2015). "Importantly, in relapsing tumors, the CD44+ cell volume expands, and CD133+ and EpCAM+ cells proportionally proliferate, indicating that the CD44+ cell population is heterogeneous within primary PDACs and relapsing tumors." (PMID 25797268, 2015).
retinal diseases (1 paper, 2022). "In some retinal diseases, the CD44 on RPE cells could greatly overexpress in the diseased/inflamed eye." (PMID 35745825, 2022).
retinitis pigmentosa (1 paper, 2024). Retinitis pigmentosa (RP) is an inherited retinal dystrophy leading to progressive loss of the photoreceptors and retinal pigment epithelium and resulting in blindness usually after several decades. "The expression of Müller cell gliosis genes known to be dysregulated in retinal pathologies such as retinitis pigmentosa, but also in DR, such as Stat3, S100a1 or CD44, were plotted to further validate the gliotic activation in our db/db mice at the molecular level." (PMID 38273366, 2024).
rhinitis (1 paper, 2023). An inflammation of the mucous membrane lining the nose, usually associated with nasal discharge. "We found that most of the immune- and cytokine-related signatures were significantly altered between AR1 and AR2, revealing a gradual increase in the expression of top genes and rhinitis marker genes (e.g., IL1RL1, CD274, and CD44) from healthy controls to AR1 and then AR2." (PMID 37206297, 2023).
salivary duct carcinoma (1 paper, 2024). An aggressive, high grade adenocarcinoma that arises from the salivary glands. "A few studied cases of salivary duct carcinoma (SDC) were positive for CD24 and CD44, while almost all cases were negative for c-KIT." (PMID 39858584, 2024).
salivary gland malignant neoplasms (1 paper, 2014). "CD24+/CD44+ subpopulation identified in our study may represent a new subtype of the cancer stem cells in HNSCC, specifically in salivary gland malignant neoplasms." (PMID 24612587, 2014).
Sandhoff disease (1 paper, 2025). A lysosomal disorder from the GM2 gangliosidosis family, caused by biallelic pathogenic variants in the HEXB gene, characterized by GM2 ganglioside accumulation in the nervous system and progressive central nervous system degeneration. "Downregulation of CD44 in TSD datasets which is in contrary of previous report in the spinal cord of mouse model of Sandhoff disease is revealing different mechanism of inflammation and neuronal loss." (PMID 40106490, 2025).
scleroderma (1 paper, 2023). Scleroderma is a rare autoimmune connective tissue disorder characterized by abnormal hardening of the skin and, sometimes, other organs. "More interactions with VECs, CECs, and LECs from scleroderma are based on the homing cell adhesion molecule (H-CAM, CD44) expressed by endothelial cells, which is among the various adhesion molecules upregulated in the serum of SSc patients." (PMID 37443817, 2023). "ECM proteins expressed by ADSCs interacted with homing cell adhesion molecules (H-CAM, CD44) on VECs, CECs, and LECs from scleroderma." (PMID 37443817, 2023).
scrapie (1 paper, 2019). A fatal disease of the nervous system in sheep and goats, characterized by pruritus, debility, and locomotor incoordination. "Furthermore, the expression profile of the CD44+ immunostaining in mice infected with the ME7 scrapie agent strain was unaltered by the route of infection." (PMID 31551718, 2019).
Seizure (1 paper, 2024). A seizure is an intermittent abnormality of nervous system physiology characterized by a transient occurrence of signs and/or symptoms due to abnormal excessive or synchronous neuronal activity in the brain. "Seizures provoke an increase in CD44 in astrocytes, at least in the isocortex and hippocampus, the two areas we examined in the human CNS and in the mouse entorhinal cortex following pilocarpine-induced seizures." (PMID 38247821, 2024).
severe combined immunodeficiency (1 paper, 2006). Severe combined immunodeficiency (SCID) comprises a group of rare monogenic primary immunodeficiency disorders characterized by a lack of functional peripheral T lymphocytes resulting in early-onset severe respiratory infections and failure to thrive. "Also, we did not observe metastasis of SUM1315 cells, with a 97% CD44+/CD24- subpopulation, in nude mice, although previous studies have shown bone metastasis of these cells in nonobese diabetic/severe combined immunodeficiency mice with humanized but not mouse bone." (PMID 17062128, 2006).
spinal stenosis (1 paper, 2023). Narrowing of the spinal canal. "In contrast, case 6, despite having full CD44 positivity (100%), displayed decreased CD73 positivity (87.4%) and presented radiological signs of degenerative spondylolisthesis and spinal stenosis." (PMID 38069151, 2023).
systemic mastocytosis (1 paper, 2023). Systemic mastocytosis (SM) comprises a heterogeneous group of rare acquired and chronic hematological malignancies that are related to an abnormal proliferation of mast cells in tissue, including bone marrow, with or without skin involvement. "For instance, the mRNA levels of the receptors CD44 and CXCR4, significantly downregulated in HMC-1.3 compared to HMC-1.2, are important for homing of stem cells, huMCs and/or huMC progenitors and have been associated with hematological malignancies, including systemic mastocytosis." (PMID 37025992, 2023).
temporal lobe epilepsy (1 paper, 2024). A localization-related (focal) form of epilepsy characterized by recurrent seizures that arise from foci within the temporal lobe, most commonly from its mesial aspect. "We found that hippocampal pyramidal neurons in temporal lobe epilepsy were also surrounded by CD44+ processes." (PMID 38247821, 2024). "Furthermore, transcriptomics of the reactive astrocytosis accompanying temporal lobe epilepsy show upregulated CD44." (PMID 38247821, 2024).
tetanus (1 paper, 2012). A serious infectious disorder that follows wound contamination by the Gram-positive bacterium Clostridium tetani. "In addition to CD44 and identified protein receptors for entry of Clostridium and Bacillus binary toxins, clostridial neurotoxins (botulinum and tetanus) use multiple cell-surface proteins and gangliosides for entry into neurons." (PMID 23236484, 2012).
thoracic tumors (1 paper, 2018). "In order to assess the effect of the MIF/CD74 pathway in the development of MPM, we derived a new human MPM cell line expressing MIF, CD74, and CD44 and able to generate orthotopic intra-thoracic tumors." (PMID 29949929, 2018).
Thromboembolism (1 paper, 2022). The formation of a blood clot inside a blood vessel that subsequently travels through the blood stream from the site where it formed to another location in the body, generally leading to vascular occlusion at the distant site. "In addition, the analysis of CD44 and TF in clinical studies may help specify their roles in the occurrence of cancer-associated thromboembolism, which remains a leading cause of cancer-related death." (PMID 35805061, 2022).
thymic tumors (1 paper, 2014). "The majority (60%) of thymic tumors had a mixed phenotype expressing low-levels of CD4 and CD8 along with a combination of CD44 and CD25." (PMID 24586935, 2014).
uterine prolapse (1 paper, 2022). Downward displacement of the UTERUS. "In summary, this study provides evidence that CD44 may be a risk factor for uterine prolapse and a novel candidate biomarker of POP." (PMID 35910471, 2022). "The occurrence of uterine prolapse was positively correlated with age, postmenopausal age, and MMP-2 and MMP-9 expression (p < 0.01) and negatively correlated with CD44 expression (p < 0.05)." (PMID 35910471, 2022). "The results indicated that the occurrence of uterine prolapse was positively correlated with age, postmenopausal age, and MMP-2 and MMP-9 expression (p < 0.01), and negatively correlated with CD44 expression (p < 0.05)." (PMID 35910471, 2022). "We believe that this is the first report to illustrate the difference in CD44 expression between POP and non-POP women, aa well as the correlation between these indicators and uterine prolapse." (PMID 35910471, 2022).
Ventricular arrhythmia (1 paper, 2023). "The inducibility of ventricular arrhythmias (VAs) was attenuated in CD44-/- HF mice compared with wild-type HF controls." (PMID 37452346, 2023).
vulvar cancer (1 paper, 1998). "Immunohistochemically detected expression of CD44 isoforms containing variant exon v6 or v3 is correlated with a poor relapse-free and overall survival in FIGO stage I vulvar cancer patients." (PMID 9792156, 1998).
Wilson disease (1 paper, 2025). A very rare inherited multisystemic disease presenting non-specific neurological, hepatic, psychiatric or osseo-muscular manifestations due to excessive copper deposition in the body. "While we identified the importance of the PrP-mediated pathway in Wilson disease, a recent study reported that CD44-mediated Cu uptake plays a significant role in immunity and cancer progression." (PMID 39922819, 2025).
xerostomia (1 paper, 2025). Dryness of the mouth resulting from reduced salivary secretion. "Given real-world variability in salivary flow and mucosal status, in vitro performance should be profiled under xerostomia-mimicking and normosalivary conditions and, for HA-targeted systems, analyzed by CD44 expression." (PMID 41012547, 2025).